IL18 (interleukin 18)
Diseases named in the same sentence as IL18 in open-access papers (continued):
Sharing a sentence is not in itself a finding about the gene and the disease.
keloid (13 papers, 2015 to 2025). An irregularly shaped, elevated mark on the skin caused by deposits of excessive amounts of collagen during wound healing. "Not only IL-18, IL-18Rα and IL-18Rβ expression was also elevated in keloid tissue compared with normal skin tissue." (PMID 39799030, 2025). "The GSEA revealed significant enrichment in several key pathways in keloid tissue, including the “IL-18 signaling pathway” (NES = 1.576, p = 0.040, FDR = 0.039) and the “IL-23 signaling pathway” (NES = 2.015, p = 0.011, FDR = 0.010)." (PMID 40051702, 2025). "Its expression depends on PI3K/mTOR, MAPK, and Sp1 pathways, making IL-18 a key mediator of fibroblast activation and a potential therapeutic target in keloid scarring." (PMID 41424791, 2025). "The interleukin-18 (IL-18) signaling drives keloid progression by promoting pathological epithelial–mesenchymal interactions between keratinocytes and fibroblasts." (PMID 41424791, 2025). "IL-18 system plays an important role in keloid pathogenesis via epithelial-mesenchymal interactions." (PMID 39799030, 2025). "Excessive secretion of mature IL-18 by keloid coculture and increased expression of IL-18R in keloid fibroblasts lead to enhanced secretion of collagen-ECM components and profibrotic cytokines such as IL-6 and IL-8." (PMID 39799030, 2025). "Studies of the expression of IL-18 and IL-18BP in keloid keratinocyte/keloid fibroblast cocultures showed a significant elevation of bioactive IL-18 whereas IL-18BP levels remained the same." (PMID 35625564, 2022). "Fibroblasts derived from patients with keloids had increased IL-18 levels, while IL-18BP levels remained the same." (PMID 35625564, 2022). "The activation of NLRP3 facilitated cleaved caspase-1 processing and promoting the release of IL-1β and IL-18, and increased the inflammatory response in keloid." (PMID 33959031, 2021). "The role of IL-18 in HS and keloid was conflicting, which inhibited the former and promoted the latter." (PMID 33959031, 2021). "It suggests that IL-18 system plays an important role in the pathogenesis of keloid through epithelial mesenchymal interaction." (PMID 33959031, 2021). "mRNA levels of pro-inflammatory cytokines IL-1β and IL-18 activated by the NLRP3 inflammasome were significantly increased in keloid fibroblasts than in normal fibroblasts." (PMID 33126764, 2020). "Although an increase of IL-1β mRNA was observed in keloid fibroblasts, it was hard to detect IL-1β and IL-18 expression levels in keloid fibroblasts in the present study." (PMID 33126764, 2020). "The addition of phosphatidylinositol 3-kinase (PI3K), mitogen activation protein kinase (MAPK), Specificity protein 1 (Sp1), and mammalian target of rapamycin (mTOR) inhibitors inhibited IL-18 secretion in keloid cocultures, suggesting their potential clinical use in the treatment of keloid." (PMID 39799030, 2025). "Furthermore, gene set enrichment analysis (GSEA) in both the training and validation datasets revealed significant enrichment of the IL-18 pathway, indicating the consistency of inflammatory signaling in keloids across different populations." (PMID 40051702, 2025). "Studies on the expression of IL-18 and its antagonist, IL-18 Binding Protein (IL-18BP), using a coculture model demonstrated severe IL-18⁄IL-18BP imbalance in keloid keratinocyte/keloid fibroblast cocultures with significant elevation of bioactive IL-18 whereas IL-18BP levels remained the same." (PMID 39799030, 2025). "IL-18 promotes keloid pathogenesis via epithelial-mesenchymal upregulation." (PMID 35625564, 2022). "Moreover, when keratinocytes and keloid fibroblasts (KK/KF) were cocultured, IL-18/IL-18BP was seriously unbalanced, which promoted the formation of keloid." (PMID 33959031, 2021). "IL-18 plays a role in keloid pathogenesis through epithelial-mesenchymal interactions." (PMID 26690141, 2015).
keloid (continued). "Various pro‐inflammatory cytokines, including IL‐6, IL‐8, IL‐18 and chemokine like factor‐1 (CKLF‐1), are significantly elevated in keloid tissue, and IL‐8 and IL‐17 are elevated in the peripheral blood of keloid patients." (PMID 39895409, 2025). "Here, we confirmed keloid NLRP3 activation (cleaved caspase-1 [P < 0.05], IL-1β [P < 0.05], IL-18 [P < 0.01]) and upregulation in Glut1 (P < 0.001) and glycolytic enzymes." (PMID 32750036, 2020). "The expression of IL-18 was much higher in the keloid patients than that of the normal control group." (PMID 39799030, 2025). "WGCNA and functional enrichment analyses revealed that these genes were primarily involved in fibrosis and inflammatory processes in keloids, such as the MAPK signaling pathway, lymphocyte and monocyte proliferation, and inflammatory pathways involving IL-18 and IL-23." (PMID 40051702, 2025). "However, the expression of cleaved caspase-1, IL-1β and IL-18 was upregulated in human keloids 7–10 days after burn compared with burn and normal skin, suggesting NLRP3-mediated inflammation in keloids and possibly contributing to a persistent inflammatory state." (PMID 38957662, 2024).
osteoporosis (13 papers, 2012 to 2025). A condition of reduced bone mass, with decreased cortical thickness and a decrease in the number and size of the trabeculae of cancellous bone (but normal chemical composition), resulting in increased fracture incidence. "Specifically, escalated levels of IL-18 were positively linked with an elevated risk of osteoporosis, confirming a potential pro-inflammatory function in its pathogenesis." (PMID 41329541, 2025). "As expected, the mediation analysis suggested that the indirect effect of IL-18 was 1.020 (95% CI: 1.000–1.040, p=0.048), with a mediation proportion of 18.9% in the CeD-osteoporosis association." (PMID 39445015, 2024). "The MR-Steiger test confirmed the causal directions from CeD to IL-18 and from IL-18 to osteoporosis." (PMID 39445015, 2024). "By using one cis-pQTL (rs5744249, located in the intron of IL18 gene) as the instrument, we found that plasma level of IL-18 was positively associated with osteoporosis risk (OR: 1.347, 95% CI: 1.115–1.626, p=0.002)." (PMID 39445015, 2024). "To classify their causality, we conducted a MR analysis to investigate the effect of IL-18 level on the risk of Osteoporosis." (PMID 32266232, 2020). "Each line of the table documents 10 items involving the SNP, EA, chromosome position, beta coefficients and SE of the SNP on the risk of IL-18 and Osteoporosis, and so on." (PMID 32266232, 2020). "To explore the causal effect of IL-18 on the development of Osteoporosis, we conducted a MR analysis in this study." (PMID 32266232, 2020). "In summary, 8 SNPs were used as IVs for estimating the causal effect of IL-18 on the development of Osteoporosis." (PMID 32266232, 2020). "The present MR study reveals that CeD is associated with an increased risk of developing osteoporosis, which may be partly mediated by upregulation of interleukin-18." (PMID 39445015, 2024). "In the present study, we identified IL-18 as mediator between CeD and osteoporosis, reflecting that IL-18 measurement may help the risk classification of osteoporosis in atypical or asymptomatic CeD patients." (PMID 39445015, 2024). "Associations of genetic variants with IL-18 and Osteoporosis." (PMID 32266232, 2020). "Results show that low IL-18 level could increase the risk of the development of Osteoporosis based on simple median method." (PMID 32266232, 2020). "As a result of simple median method, we get the SE (−0.001; 95% CI−0.002 to 0; P = 0.042), which means low IL-18 level could increases the risk of the development of Osteoporosis." (PMID 32266232, 2020). "This means that low IL-18 level could increase the risk of the development of Osteoporosis." (PMID 32266232, 2020). "Upon conducting a heterogeneity assessment, IL-19 was excluded from subsequent analysis due to significant heterogeneity, while the remaining two factors, IL-18 and Artemin, demonstrated remarkable links with osteoporosis." (PMID 41329541, 2025). "Estrogen deficiency curtailed osteogenic differentiation of BMSCs by promoting the Capsase-1/GSDMD/IL-18 and IL-1β pyroptosis pathways, culminating in osteoporosis, while NLRP3 knockdown fostered bone formation." (PMID 38895114, 2024). "Among the candidate inflammatory cytokines, only interleukin-18 was observed to mediate the effects of CeD on osteoporosis, with an indirect OR of 1.020 (95% CI: 1.000–1.040, p=0.048) and a mediation proportion of 18.9%." (PMID 39445015, 2024). "IL-18 demonstrated a protective effect against osteoporosis in our study, possibly because IL-18 promotes osteogenic differentiation of hBMSCs through the SLC7A5/c-MYC pathway." (PMID 39091505, 2024). "Accordingly, administration of IL-18 antagonists can improve osteoporosis and reduce pro-inflammatory cytokines in ovariectomized mice." (PMID 39445015, 2024). "In this study, we found that the protein expression of IL-18 was colocalized with osteoporosis, further supporting its role in the bone mass deterioration in CeD patients." (PMID 39445015, 2024).
osteoporosis (continued). "The results provided evidence for colocalization between the protein expression of IL-18 and osteoporosis (PP.H4 = 0.56)." (PMID 39445015, 2024). "The study in postmenopausal women with osteoporosis demonstrated that single-nucleotide variants in NLRP3 inflammasome pathway genes activating pro-inflammatory cytokines IL-1β and IL-18 production are associated with osteoporosis severity." (PMID 37958752, 2023). "Here Z (e.g., SNPs) represents IVs, X is phenotype (e.g., IL-18), and Y is the disease (Osteoporosis)." (PMID 32266232, 2020). "Further, in vivo and in vitro studies confirmed that OC-Exo-packaged miR-30a-3p was transferred to OBs and inhibited bone formation, possibly via targeting IKBKG to initiate caspase-1 activation and the secretion of IL-1β and IL-18, thus accelerating the progression of osteoporosis." (PMID 40110632, 2025). "The results also demonstrated that IL-18 could mediate the effect of CeD on osteoporosis (indirect effect, OR: 1.015, 95% CI: 1.001–1.029, p=0.041), with a mediation proportion of 14.0%." (PMID 39445015, 2024). "In summary, our MR research indicates that patients with CeD are at higher risks of developing osteoporosis, which may be partly mediated by the increased level of IL-18." (PMID 39445015, 2024). "Bayesian colocalization analysis supported the role of interleukin-18 in osteoporosis." (PMID 39445015, 2024). "Alongside with these reports, our results indicated that IL-18 may also serve as a potential target for the prevention and treatment of osteoporosis in patients with CeD." (PMID 39445015, 2024). "Additionally, plasma IL-18 levels appeared to play an important role in mediating the relationship between CeD and osteoporosis." (PMID 39445015, 2024). "The colocalization analysis supported the connection between IL-18 and osteoporosis." (PMID 39445015, 2024). "Among the inflammatory cytokines, we observed that IL-18 might mediate the effect of CeD on osteoporosis." (PMID 39445015, 2024). "Recent reports have shown that IL-18 maintain a long-standing inflammation status in CeD patients and can up-regulate the expression of key osteoclastogenic regulators, pointing towards a mediation role in the CeD-induced osteoporosis." (PMID 39445015, 2024). "The administration of IL-18 antagonists alleviated osteoporosis in OVX mice." (PMID 38895114, 2024). "Thirdly, despite being documented as a potential mediator, the exact biological pathway though which IL-18 promotes osteoporosis in CeD remains unclear." (PMID 39445015, 2024). "Moreover, reduction of IL-18BP in PBMCs isolated from osteoporotic patients indicated increased IL-18 signaling in osteoporosis [84•]." (PMID 35567665, 2022). "The number of the samples for IL-18 and Osteoporosis GWAS data is the baseline for our MR analysis." (PMID 32266232, 2020). "Till now, it is not clear that the level of IL-18 is the causal or consequence of the development of Osteoporosis." (PMID 32266232, 2020). "IL-18, IL-6 and hs-CRP are risk factors for trabecular bone destruction in osteoporosis patients." (PMID 31258577, 2019). "Therefore, despite IL-1 and IL-18 playing pathological roles in osteoporosis, targeting osteoporosis with IL-1-blocking monotherapy may be insufficient to prevent osteoporosis." (PMID 35567665, 2022). "Although current advantages on investigating the relationship between IL-18 and Osteoporosis, it is still not clear whether IL-18 is the consequent or causal effect of the Osteoporosis." (PMID 32266232, 2020). "In humans, IL-18, one of the downstream signaling events of the NLRP3 inflammasome, is elevated in patients with osteoporosis, and therapeutics targeting the NLRP3 inflammasome are of interest for osteoporosis treatment." (PMID 38221578, 2024). "Increased expression of related indicators in this study suggested the effect of inflammatory factors such as IL-18, IL-6 and hs-CRP on osteoporosis." (PMID 31258577, 2019).
osteoporosis (continued). "Hence, the immune microenvironment, comprising immune cells and inflammatory factors (IL-1β, IL-18, IL-17, IL-6, and TNF-α), plays a pivotal regulatory role in bone metabolism and contributes to the pathogenesis of osteoporosis." (PMID 38895114, 2024). "However, there are no direct studies on the role of IL-18 in pathogenesis of post menopausal osteoporosis and if inhibiting this inflammatory cytokine may lead to any osteoprotective effects." (PMID 27649785, 2016).
Splenomegaly (13 papers, 2015 to 2026). Abnormal increased size of the spleen. "Active IL-18 levels were associated with clinical features such as rash and splenomegaly and correlated with specific cytokines." (PMID 42131320, 2026). "Accordingly, mice lacking COX2 were more susceptible to A. phagocytophilum, had a defect in IL-18 secretion and exhibited splenomegaly and damage to the splenic architecture." (PMID 27482714, 2016). "Elevated active IL-18 levels were associated with rashes and splenomegaly." (PMID 42131320, 2026). "Analysis of IkkeK38A/K38ATbk1fl/D135NCx3cr1-Crewt/tgIl1.18.33r-/- revealed that combined IL-1R1, IL-18R1 and IL-33R deficiency ameliorated splenomegaly, granulocytosis, and monocytosis, revealing an important role for IL-1, IL-18, and IL-33 in driving systemic inflammation in these animals." (PMID 38167258, 2024). "A 38-year-old woman in complete AOSD remission without medication presented with impaired liver function, low platelet count, mild fever, abdominal pain, splenomegaly, and elevated ferritin and IL-18 levels at 30 gestational weeks." (PMID 33627085, 2021). "Considering the findings such as mild fever, elevated ferritin level, high level of IL-18, splenomegaly, and good fetal status, she was ultimately diagnosed with recurrence flare of AOSD by us and some rheumatologists." (PMID 33627085, 2021). "Under recessive model, TT genotype of IL-18 (rs1946518) was statistically correlated with both splenomegaly and AST concentration in serum compared with GG/GT genotype (p = 0.018, p = 0.034, respectively)." (PMID 31428046, 2019). "Specific findings of the flare of AOSD such as fever, splenomegaly, elevated ferritin and IL-18 levels, and fetal status could be useful findings for differentiation from HELLP syndrome and AFLP in the third trimester." (PMID 33627085, 2021). "Taking together T-cell-derived IFN-γ play a prominent role in IL-15 mediated toxicityRegarding splenomegaly and hepatomegaly other cytokines induced by IL-15 like TNF-α or IL-18 might also be implicated." (PMID 27356750, 2016). "Probably due to the unaffected IFN-γ concentration, IL-18 deficiency in MRLlpr mice affects neither survival nor the accumulation of DN T-cells accompanied by lymphadenopathy and splenomegaly." (PMID 26465326, 2015). "Our data demonstrated that IL-18 is not essential for the development of characteristics associated with hyperinflammatory disease, including hyperferritinaemia, splenomegaly and cytokine storm, mirroring the results observed in response to direct inhibition of IL-18 signalling." (PMID 38775430, 2024). "WT and Lrrk2-deficient mice were infected with Salmonella enterica serovar Typhimurium, and three markers of inflammation were measured: IL-18, IFN-γ, and splenomegaly." (PMID 32111741, 2020). "Inhibition of the NLRP3 inflammasome, or downstream caspase-1, prevented MAS-mediated upregulation of plasma IL-18 but interestingly did not alleviate key features of hyperinflammatory disease including hyperferritinaemia and splenomegaly." (PMID 38464243, 2024). "Inhibition of the NLRP3 inflammasome or the downstream caspase-1 prevented MAS-mediated upregulation of IL-18 in the plasma but, interestingly, did not alleviate key features of hyperinflammatory disease including hyperferritinaemia and splenomegaly." (PMID 38775430, 2024). "However, in the CpG-induced model of MAS, NLRP3 and IL-18 were not required for the characteristic manifestations of hyperinflammation, including splenomegaly and hyperferritinaemia." (PMID 38775430, 2024).
cryopyrin-associated periodic syndrome (12 papers, 2013 to 2025). Cryopyrin associated periodic syndrome (CAPS) defines a group of autoinflammatory diseases, characterized by recurrent episodes of systemic inflammatory attacks in the absence of infection or autoimmune disease. "Consistent with the NLRP3 inflammasome role in interleukin (IL)-1β and IL-18 maturation, cryopyrinopathies are associated with excessive production of these cytokines." (PMID 30388107, 2018). "IL-1β and IL-18 are the pivotal cytokines in autoinflammatory diseases such as cryopyrin-associated periodic syndromes (CAPS) group and Schnitzler syndrome (SchS) which are regularly associated with urticarial rash." (PMID 24490166, 2013). "Mutated NLRP3 assembles a hyperactive inflammasome, which causes excessive secretion of interleukin (IL)-1β and IL-18 and, ultimately, a spectrum of autoinflammatory disorders known as cryopyrinopathies of which neonatal-onset multisystem inflammatory disease (NOMID) is the most severe phenotype." (PMID 30388107, 2018). "Cryopyrin-associated periodic syndromes (CAPS) are diseases strongly associated with excessive IL-1β and IL-18 production." (PMID 35455985, 2022). "The prevalence of organ-specific phenotypes (e.g., cutaneous phenotypes in NLRP1-associated syndromes) or cytokine-driven diseases (IL-18 in NLRC4-associated syndromes compared to IL-1 in NLRP3/Cryopyrin-Associated periodic Syndromes) may be largely due to differential transcriptional regulations." (PMID 33138274, 2020). "Accordingly, NLRP3 gain-of-function mutations, which cause a spectrum of autoinflammatory disorders known as cryopyrin-associated periodic syndromes (CAPS), are associated with excessive IL-1β and IL-18 production." (PMID 30388107, 2018). "Cryopyrin-associated periodic syndromes are disorders caused by mutations in the NLRP3 gene, previously known as cold-induced autoinflammatory syndrome 1, which results in uncontrolled processing of IL-1β and IL-18." (PMID 28588486, 2017). "In fact, LPS-stimulated human blood-derived macrophages and monocytes from patients with cryopyrin-associated periodic syndrome (CAPS) treated with OLT1177 presented a decreased level of IL-1β and IL-18." (PMID 37360532, 2023). "Cryopyrin-associated periodic syndromes (CAPS) are caused by a mutation in NLRP3 inflammasome, resulting in increased IL-1β and IL-18 production, but impaired production of the anti-inflammatory IL-6 and IL-1RA cytokines." (PMID 29515591, 2018).